DPP4 (dipeptidyl peptidase 4)
Diseases named in the same sentence as DPP4 in open-access papers (continued):
Sharing a sentence is not in itself a finding about the gene and the disease.
diabetes (continued). "Indeed, we reported that both DPP-4 inhibitor and GLP-1RA had a protective effect against β-cell dysfunction in a diabetic rodent model and that the effectiveness was more remarkable at the early phase of diabetes compared with the advanced stage of diabetes." (PMID 34484124, 2021). "However, DPP-4 inhibitors only provide a modest decrease in glycated haemoglobin without evidence of benefits on complications of diabetes, including cardiovascular outcomes, demonstrated in randomised clinical trials." (PMID 34256874, 2021). "Anagliptin, another DPP-4 inhibitor, was shown to decrease low-density lipoprotein cholesterol (LDL-C) level to a greater extent than that by sitagliptin in the Randomized Evaluation of Anagliptin vs. Sitagliptin On low-density lipoproteiN cholesterol in diabetes (REASON) trial." (PMID 32539832, 2020). "However, improvement of cardiovascular outcomes by adding DPP-4 inhibitors to usual care in patients with diabetes mellitus and cardiovascular diseases has not yet been proved." (PMID 32539832, 2020). "Treatment with DPP-4 inhibitors significantly reduced the progression of diabetic retinopathy in patients after propensity score matching when compared to treatment with other oral diabetes medications, independent of glycemic control." (PMID 32190049, 2020). "Furthermore, dipeptidyl peptidase 4 (DPP-4) inhibitors (also known as gliptins), which are second-line oral anti-diabetic drugs, have been demonstrating anti-inflammatory properties and prevention of BRB breakdown in preclinical models of diabetes." (PMID 32759750, 2020). "The availability of large quantities of human soluble DPP4 proteins facilitates further structural studies and substrate and inhibitor discovery to enhance the biochemical understanding of this protease for developing therapeutics for MERS, diabetes, cancer, fibrosis and atherosclerosis." (PMID 33218025, 2020). "Intestinal cells apoptosis were checked by tunnel assay, Incretin hormones secretion and dipeptidyl peptidase 4 (DPP-IV) activity were analyzed through ELISA and immunohistochemistry was used to determine the insulin expression of intestine at different time interval during diabetes progression." (PMID 31380261, 2019). "Since DPP-4 rapidly cleaves and inactivates the incretin hormones (GLP-1 and GIP), which are essential for glucose regulation, its blockade has been investigated as a way of ameliorating glycemia in diabetes through preservation of the impaired incretin action." (PMID 31366085, 2019). "Recent studies reported that sodium glucose cotransporter 2 (SGLT2) inhibitors reduced the cardiovascular morbidity and mortality in patients with type 2 diabetes mellitus (T2DM) compared to placebo in contrast to no reduction with dipeptidyl peptidase 4 (DPP4) inhibitors." (PMID 29895330, 2018). "Interestingly, urinary DPP-4 activity was found to be significantly higher in individuals with type 2 diabetes and albuminuria compared with non-albuminuric diabetes patients or healthy individuals." (PMID 29491123, 2018). "Given the complexity of the clinical effects exhibited by DPP-4 inhibitors in diabetes, it may not be entirely informative to refer to them solely as incretin-based drugs." (PMID 29310647, 2018). "The “Cardiovascular Outcomes in Participants with Type 2 Diabetes Mellitus” study, which compares CV outcomes of several drug classes (SGLT-2 inhibitors, GLP-1 RAs, DPP-4 inhibitors, Thiazolidinedione, Sulfonylureas and Insulin) could give further insight into this question." (PMID 29020969, 2017). "The results of the present study correspond well with those of previous studies showing that the CVD (including HF) hospitalization rate did not increase with the use of incretin-based drugs or DPP-4 inhibitors compared with the use of oral antidiabetic drugs in patients with diabetes." (PMID 28640111, 2017).
diabetes (continued). "DPP-4 enzymatic activity in either the kidney or plasma was significantly higher in the diabetic CD-1 mice than in the control mice; minor induction of DPP-4 activity in diabetes was also observed in the 129Sv strain, although it was significantly lower than in the CD-1 mice." (PMID 27425816, 2016). "Moreover, currently ongoing trials do not specifically focus on early diabetes as a target of intervention and we therefore believe that our study will contribute to a better understanding of cardiovascular effects of DPP-4 inhibitors in early diabetes." (PMID 27733180, 2016). "In contrast to no significant improvement of glucose tolerance by DPP-4 inhibition in db/db mice at the late stage of severe diabetes, linagliptin is reported to significantly reduce blood glucose and improve glucose tolerance in younger db/db mice at the early stage of diabetes." (PMID 25986579, 2015). "Of the 128 diabetes patients not treated with metformin 67 (27.8%) were treated with diet alone, 35 (14.5%) with sulfonylurea alone, 23 (9.5%) with insulin alone and 1 (0.4%) with sulfonylurea and dipeptidyl peptidase-4 inhibitor (sitaglipin)." (PMID 26074965, 2015). "Therefore, short-term treatment with either DPP-4 inhibitors or alpha GI does not ameliorate endothelial dysfunction in patients with diabetes." (PMID 25074318, 2014). "However, the administration of GLP-1 is not effective as a treatment for diabetes, because the protein is rapidly degraded by dipeptidyl peptidase-4 (DPP-4)." (PMID 24351817, 2013). "Therefore, drugs capable of inhibiting the DPP4 dipeptidyl peptidase catalytic activity, which are currently FDA-approved for treatment of diabetes, may have utility in targeting CML LSCs." (PMID 23651669, 2013). "Notably, DPP4, also known as CD26, contributes to glucose homeostasis by inactivating glucagon-like peptide-1 (GLP-1), an incretin hormone that downregulates glycaemia, and DPP4 inhibitors have been a therapy for managing type 2 diabetes mellitus (T2DM) since 2006." (PMID 40293537, 2025). "In addition to their effects on glucose metabolism, DPP4 inhibitors such as sitagliptin, vildagliptin, linagliptin and saxagliptin also inhibit the degradation of NPY, thereby increasing its blood concentration in healthy individuals and patients with type 2 diabetes mellitus." (PMID 40490517, 2025). "However, since this is a relatively short-term observation of a single case, it is necessary to accumulate more cases in the future to determine whether the combination of a DPP-4 inhibitor and an SGLT2 inhibitor is effective in the treatment of CMT complicated by diabetes mellitus." (PMID 40951209, 2025). "Moreover, non-diabetic plasma-treated SVFs are capable of mitigating diabetes-induced plasma DPP4 activity, liver inflammation, and insulin resistance, which may be mediated by suppressing M1 cytokines and increasing IL-10 and Tregs in the adipose tissue." (PMID 39125659, 2024). "For women of reproductive years living with type 2 diabetes, the relative merits of using non-insulin pharmacotherapies vs diabetes technology (dipeptidyl peptidase-4 inhibitors, glucagon-like peptide-1 receptor agonists and sodium−glucose cotransporter 2 inhibitors) are unknown." (PMID 38967667, 2024). "However, when observational (mostly retrospective) studies compared clinical outcomes in DPP4 inhibitor users vs. non-users among diabetes patients with COVID-19, the overall results regarding the risk of progression towards more severe forms of disease and mortality were heterogenous." (PMID 37374918, 2023). "Most importantly, our findings reveal that nondiabetic plasma-treated SVFs are capable of mitigating diabetes-induced plasma DPP4 activity, liver inflammation, and insulin resistance and that may be mediated through suppressing M1 cytokines but increasing IL-10 and Tregs in adipose tissue." (PMID 35883204, 2022).
diabetes (continued). "Some authors hypothesize that DPP4 inhibitors could represent a new strategy to support the treatment of COVID-19 in patients, with or without diabetes, by reducing the viral entry and replication into the respiratory tract and by hampering the inflammation and cytokine storm within the lungs." (PMID 34360529, 2021). "In addition to the many drugs currently used to treat diabetes (e.g., nateglinide, metformin, dipeptidyl peptidase-4 (DPP-4) inhibitors, linagliptin, and α-glycosidase inhibitors), there are ongoing efforts to develop new natural drugs to the treatment of diabetes without side effects." (PMID 31835423, 2019). "Additionally, vildagliptin, a DPP4 inhibitor, increased survival rates of diabetic, but not non-diabetic mice, suggesting that DPP4 may have a unique role in diabetes." (PMID 28587613, 2017). "It is known that during the progress of diabetes and obesity through high fat diet in experimental rodent models, the development of autonomic neuropathy occurs, which could alter the gut-brain axis and the enteric GLP-1 signal, consequently hampering the therapeutic efficacy of DPP4 inhibitors." (PMID 26828649, 2016). "Thus, DPP4 inhibition also plays an important role irrespective of the duration of diabetes." (PMID 26284071, 2015). "Suppression of glucagon action on target organs may be a secondary mechanism underlying the antihyperglycemic efficacy of GLP-1 analogs and DPP-4 inhibitors, but there are no approved treatments for diabetes that directly target glucagon secretion or glucagon action in target organs." (PMID 23185367, 2012). "Though pancreatitis is common among other diabetes medications, such as GLP-1 mimetics and dipeptidyl peptidase-4 (DPP-4) inhibitors, it is not recognized by the FDA as an adverse effect of SGLT-2 inhibitor use." (PMID 38910717, 2024). "Similar to our findings, clinical trials evaluating DPP4 inhibitors have reported a significant reduction in fibrosis scores and liver enzymes (AST and ALT levels) in NAFLD patients without diabetes." (PMID 37739179, 2023). "Nonetheless, it is interesting to note that non-insulin glucose-lowering drugs, not only DPP4 inhibitors and SGLT2 inhibitors but also GLP1 analogues, are starting to be used in hospital diabetes management." (PMID 35315989, 2022). "Altogether, these results suggest that diabetes induces JNK activation and DPP4 protein expression and non-diabetic plasma diminishes diabetes-induced JNK activation and DPP4 protein expression in the adipose tissue of diabetes." (PMID 34043673, 2021). "Collectively, these results indicate that diabetes induces ICAM, FMO3, and DPP4 expression in the liver, and non-diabetic plasma injected into the adipose tissue reduces the expression of those proteins in the liver of diabetic mice." (PMID 34043673, 2021). "In conclusion, combination of DPP-4 inhibitor and SGLT2 inhibitor exerts more beneficial effects on β-cell mass and function, especially in an early phase of diabetes rather than an advanced phase." (PMID 34373487, 2021). "Thus, we determined incretin levels in addition to glucagon level using the bioassays in type 2 diabetes mellitus (T2DM) subjects with or without treatment of DPP-4 inhibitor, to evaluate whether these assays can accurately measure bioactivity of these peptides." (PMID 32390941, 2020). "In contrast, anagliptin treatment does not appear to affect serum parameters related to diabetes and dyslipidemia in our NASH model, whereas it markedly inhibits DPP-4 activity and increased active GLP-1 levels in the serum." (PMID 31969650, 2020). "Finally, although targeting DPP-4-GLP-1 signalling may improve exercise tolerance in HF patients, it has not been approved by any organizations, and we cannot draw a conclusion regarding whether type 2 diabetes mellitus patients with HF could benefit more from treatment." (PMID 31870322, 2019).
diabetes (continued). "Collectively, the findings from these studies suggest that both DPP-4 inhibitors and GLP-1R agonists exert beneficial actions on EDH in diabetes through mechanisms independent of their glucose-lowering effects." (PMID 31370156, 2019). "In this study, we sought to compare DPP-4 inhibitors with intermediate-acting NPH insulin in terms of effectiveness and safety for the management of patients with type 2 diabetes mellitus not controlled on metformin and sulfonylureas." (PMID 29713649, 2018). "Thus, clinically, DPP-4 inhibitors may improve albuminuria and may have a renoprotective effect; however, further study is necessary to identify whether long-term treatment with several DPP-4 inhibitors in patients with diabetes may maintain renal function as well as reduction of albuminuria." (PMID 28761658, 2017). "Here we investigated whether the plasma soluble form of DPP4 is associated with the prevalence of coronary artery disease (CAD) with and without diabetes mellitus (DM)." (PMID 27654253, 2016). "It was also reported that sitagliptin, another DPP-4 inhibitor, improves histological changes of NAFLD in mice that have dietary obesity with or without diabetes." (PMID 27462372, 2016). "In the current study, we demonstrate that the DPP-4 inhibitor MK626, which has appropriate pharmacokinetics in mice, preceded by a short-course of low-dose anti-CD3 generated durable diabetes remission in new-onset diabetic non-obese diabetic (NOD) mice." (PMID 25268801, 2014). "Participants were categorized into three groups: non-users of diabetes medications (n=271), users of non-GLP-1-based antidiabetic therapies (n=46), and users of GLP-1 receptor agonists (GLP-1RA) or DPP4 inhibitors (DPP4i) (collectively termed GLP-1 targeting agents; n=26)." (PMID 41542041, 2026). "Pharmacological options for diabetes treatment include sulfonylureas, glucagon-like peptide 1 (GLP-1) agonists, and dipeptidyl peptide-4 (DPP-4) inhibitors; while non-pharmacological strategies involve regulating dietary energy intake, increasing physical activity, and enhancing energy expenditure." (PMID 41048425, 2025). "SGLT2 inhibitors showed robust respiratory protection that appeared largely independent of diabetes status, GLP-1 receptor agonists may provide benefit in obesity, and DPP-4 inhibitors offered limited advantage with a potential asthma risk." (PMID 41567683, 2025). "However, with advancements in diabetes treatment, more effective therapies have emerged for T2DM patients with these comorbidities, which has led to repositioning the role of DPP-4 inhibitors, primarily in T2DM patients without these conditions." (PMID 38975525, 2024). "Our previous meta-analysis demonstrated that DPP-4 inhibitor and GLP-1 Ras may help improve exercise capacity in HF patients with or without diabetes, but these trials showed no improvement in LVEF, except in a trial with a small sample size." (PMID 34759887, 2021). "A positive correlation of ACE2 and DPP4 with TMPRSS2 was lacking in pancreatic cancer and diabetes." (PMID 33796097, 2021). "Finally, we believe this is the first clinical investigation of the effects of DPP4 inhibition on immune lymphoid cells of innate immunity, namely ILC-1, ILC-2 and ILC-3 cells in AT and blood in obese persons without diabetes." (PMID 32881912, 2020). "Interestingly, there are currently clinical trials evaluating the efficacy and safety of DPP4 inhibitor sitagliptin for the treatment of NAFLD and in steatosis irrespective of diabetes in NASH." (PMID 30824564, 2019). "However, the effect of DPP-4 inhibitors on HF is still unknown, and studies on EVO to understand its impact on diabetes and its complications, including DCM, are lacking." (PMID 37009790, 2023). "Two ongoing clinical trials are assessing whether addition of DPP-4 inhibitors on the basis of insulin therapy can help improve the severity of COVID-19 (NCT04341935; NCT04542213), which may also be extended to patients without diabetes mellitus." (PMID 34867819, 2021).
diabetes (continued). "Finally, we examined whether the injection of non-diabetic plasma reverses M1 cytokine expression, plasma DPP4 activity and CCL2 levels, systemic inflammation, and glucose intolerance in diabetes." (PMID 34043673, 2021).
type 2 diabetes (1,115 papers, 2008 to 2026). "Clinical data concerning DPP4’s role in comorbidities associated with severe COVID-19, particularly in type 2 diabetes (T2D) and cardiometabolic diseases, support its potential involvement in SARS-CoV-2 infection and the pathogenesis of COVID-19 and LC." (PMID 40431631, 2025). "DPP-4 inhibitors have a low risk of hypoglycemia when used as monotherapy and can be safely prescribed to older adults with type 2 diabetes in Japan." (PMID 40607140, 2025). "In this large retrospective cohort study, we found that GLP-1 RAs were associated with significantly lower CV risk in patients with type 2 diabetes and BMI 25 or more compared with matched patients using DPP-4 inhibitors." (PMID 40920377, 2025). "Some studies demonstrate that certain DPP4 inhibitors increase the risk of HF hospitalization in patients with type 2 diabetes." (PMID 41141478, 2025). "Due to their low risk of hypoglycemia and neutral effect on body weight, DPP-4 inhibitors are widely used in patients with type 2 diabetes (T2DM)." (PMID 41018201, 2025). "Clinical evidence continues to underscore the potential of DPP-4 inhibitors in mitigating cerebrovascular risk among patients with type 2 diabetes." (PMID 40771927, 2025). "DPP-4 inhibitors, such as sitagliptin and saxagliptin, are used in type 2 diabetes to improve glycemic control with a low risk of hypoglycemia." (PMID 39594624, 2024). "Drugs like gliptins (DPP-4 inhibitors), commonly prescribed for type 2 diabetes, have also been linked to BP." (PMID 39451595, 2024). "When compared to metformin alone, the use of DPP-4 inhibitors in the treatment of patients with type 2 diabetes was associated with increased serum BDNF levels and improved cognitive functions." (PMID 38510866, 2024). "The use of DPP-4 inhibitors in the treatment of patients with type 2 diabetes was associated with increased serum BDNF levels and improved cognitive functions." (PMID 38510866, 2024). "Unfortunately, the various synthetic drugs used to treat type II diabetes (DPP4 inhibitors) typically cause more serious side effects, gastrointestinal adverse reactions, allergic reactions, skin-related side effects, and musculoskeletal disorders." (PMID 38255913, 2024). "Previous cohort studies on individuals with type 2 diabetes have linked treatment with DPP-4 inhibitors (DPP-4i) to various cancers including thyroid tumors, pancreatic cancer, and cholangiocarcinoma." (PMID 39390508, 2024). "In elderly patients with type 2 diabetes, DPP4 inhibitor decreases the risk of cognitive dysfunction compared to sulfonylureas." (PMID 37575299, 2023). "Currently, GLP-1 receptor agonists and dipeptidyl peptidase-4 (DPP-4) inhibitors of GLP-1 degradation have been identified as pharmacological targets for the treatment of type 2 diabetes, as well as to promote satiety and body weight loss." (PMID 37508442, 2023). "A recent human study showed that DPP4 inhibitors administration was significantly associated with GD exacerbation in patients with GD and type 2 diabetes." (PMID 37350750, 2023). "This cohort study examines the association of sodium-glucose cotransporter 2 vs dipeptidyl peptidase-4 inhibitor use with the incidence of obstructive airway disease and exacerbation events in patients with type 2 diabetes." (PMID 36648944, 2023). "The DPP4 inhibitors are effective and safe hypoglycemic therapy for type 2 diabetes that are effective orally and associated with a low risk of hypoglycemia, weight gain, or other adverse events on a solid basis." (PMID 35630534, 2022). "In this study, use of GLP-1 receptor agonists was associated with better outcomes compared with use of DPP-4 inhibitors among patients with type 2 diabetes and advanced-stage chronic kidney disease." (PMID 35254430, 2022). "We conducted a meta-analysis to evaluate the risk of gallbladder or biliary diseases associated with dipeptidyl peptidase 4 inhibitors (DPP4i) in patients with type 2 diabetes." (PMID 36271423, 2022).